IL10 (interleukin 10)
Diseases named in the same sentence as IL10 in open-access papers (continued):
Sharing a sentence is not in itself a finding about the gene and the disease.
infection (continued). "Interleukin-10 (IL-10) and other anti-inflammatory cytokines have a central role in infection, preventing host damage by limiting immune response, and can be produced because of virus replication." (PMID 36992353, 2023). "Collectively, M-B cells, a unique subset of B lymphocytes, contribute to the EM-mediated host defense against infections through their prominent production of IL-10." (PMID 36719648, 2023). "Collectively these observations suggest that granulocyte-derived IL-10 regulates select proinflammatory responses to promote S. aureus persistence in the galea during craniotomy infection." (PMID 37179295, 2023). "BALB/c mice depleted of Treg cells before infection with 1 × 103 spirochetes harbored a higher borrelial load in the hearts and exhibited higher levels of serum interleukin-10 five weeks later." (PMID 36839461, 2023). "Key innate inflammatory cytokines, including TNFα, IL-6, IFNα, IL-10, IL-15, and IL-18, were all significantly elevated early during infection (days 1–5) compared to HCs." (PMID 36752598, 2023). "Several plasma cytokines had an increased fold change following infection with the most robust increases observed with CXCl10, TNFα, IL-10, and IL-1RA, corroborating previously published data." (PMID 37857783, 2023). "The results in serum showed that the level of pro-inflammatory cytokine IL-1β and IL-6 dramatically increased and the level of anti-inflammatory cytokine IL-10 considerably dropped after CsA infection." (PMID 38259457, 2023). "Firstly, DMI maintained the homeostasis of inflammation by reducing the level of proinflammatory (Il6 and Il1b) and anti-inflammatory (Il10) cytokines in vivo and in macrophages during infection." (PMID 36882813, 2023). "The cytokine IL-10 is produced by multiple immune cells including Th1 cells during infection and regulates the immune response to minimise collateral host damage." (PMID 38074197, 2023). "Surprisingly, we found that IL-4, IL-5, IL-6, IL-10, and IL-13 levels reached peaks after 30 days of infection and then decreased in a time-dependent manner." (PMID 37691941, 2023). "Although IL-10 is expressed by microglia and monocytes during infection, this source appears to have little impact on S. aureus survival." (PMID 37179295, 2023). "Infection decreased IL-10 levels in interstitial macrophages: however, enhanced IL-10 levels in lymphocytes from the lung were observed." (PMID 37112697, 2023). "Since PMNs and G-MDSCs have been reported to produce IL-10, which was corroborated by our intracellular cytokine staining, we next examined craniotomy infection in Mrp8CreIL-10 fl/fl mice with WT littermates as controls." (PMID 37179295, 2023). "aureus, Δlgt S. aureus induced low levels of PGE2, IL-1β, IL-6, IL-10, and IL-8 secretion into neutrophil supernatants after infection of neutrophils for 9 h at MOI 3:1 and MOI 10:1 (P < 0.01, P < 0.001)." (PMID 37168122, 2023). "infection helped to identify a subset of IL-35 plasma cells which is induced during infection together with IL-10 plasma cells and highlighted the role of IL-35 Bregs as essential regulators of the immune system." (PMID 37849749, 2023). "The anti-inflammatory cytokine il-10 was upregulated by infection at 6 and 9 h, but its expression levels at the remaining sampling points were similar to those before infection." (PMID 37629124, 2023). "Levels of IL-6, TNFα, IL-10, and other cytokines are significantly increased with infection; elevation of IL-6 and IL-10 is a reliable indicator of a more severe disease." (PMID 36771194, 2023). "Several studies have suggested that MDSCs are the predominant IL-10-producing cells in tumors and infections." (PMID 36776848, 2023). "S. iniae-infected channel catfish continued to show the upregulated expression of IL-10 6–48 h after infection, with a peak at 48 h." (PMID 37513733, 2023).
infection (continued). "With the infection time, the host immune response shifted to Th2 type, producing IL-4, IL-5, IL-10, IL-13, and TGF-β, and promoting the formation of fibrosis." (PMID 37375483, 2023). "For example, in primary Coxiella burnetii infection, B cells defend against infection by secreting high levels of IL-10." (PMID 37759658, 2023). "For example, Sb induces high levels of IgA and interleukin 10 in the bowel, and these participate in the immunomodulatory response to infection." (PMID 37400812, 2023). "We find that CVB3 infection induced a robust up-regulation of IL-10 in the intestine and cecal patch at 3 days post infection." (PMID 37896753, 2023). "It is worth pointing out that high levels of IL-10 were also detected in a study of asymptomatic infection occurring in Singapore at the beginning of the COVID-19 pandemic." (PMID 37219944, 2023). "For B cells, we found that mice showed similar clonal expansion of B10 (B cells that produce IL-10) and memory B cells in the spleen after infection." (PMID 37039643, 2023). "The results show that SVCV infection induced carp IL-10 mRNA and protein expression, both in vitro and in vivo." (PMID 38004823, 2023). "For group B, compared with pre-infection, the level of IL-10 was increased at 1 wpi followed by attenuation; it was extremely increased (p < 0.01) at 1 wpi and significantly decreased (p < 0.05) at 5 wpi." (PMID 37152685, 2023). "By day 7 p.i., the quantity of IL-10 in the serum was significantly elevated in the Bhlhe40−/− mice, suggesting an early role for Bhlhe40 in suppressing IL-10 expression after infection." (PMID 37843306, 2023). "Among the mentioned cytokines, the expression level of IL-4 compared to IL-10 was significantly higher at the end of the infection period than at the beginning (P<0.0001)." (PMID 36779192, 2023). "Previous studies reported that in sea bass, IL-10 was induced 24 h and 10 days after infection, with a low-level increase at 3 dpi, or was increased at 24 and 72 hpi (3 dpi) without any differences at longer times points." (PMID 38068937, 2023). "In contrast, infection with C. perfringens resulted in a significant (p ≤ 0.01) increase in IL-10 mRNA transcripts in all intestinal segments studied." (PMID 38164397, 2023). "This revealed some pathogenic phenotypes associated with infection and critically that vaccination allows maintenance of testicular homeostasis, likely by preventing significant influx of CD4 T cells and promoting IL10 production." (PMID 36799886, 2023). "As in the experiments above, our data shows that cells infected with exosome-free L. braziliensis produced significantly less IL-1β, TNF, IL-10 and IL-6 upon infection." (PMID 37841240, 2023). "Although CQ treatment increased the number of TNF-producing macrophages, it reduced the levels of TNF and increased the levels of IL-10 production by these cells during infection." (PMID 38256880, 2023). "These responses provided ample evidence that IL-10 is a key immunomodulatory cytokine during infection and is also required for optimal pathogen clearance and ameliorates immunopathological status." (PMID 37513733, 2023). "Rotavirus-infected rats exhibited higher levels of interleukin-2 (IL-2), and interleukin-10 (IL-10), and the increased levels were partially reversed when aspirin was administered in conjunction with infection." (PMID 37848986, 2023). "In this regard, IL-10 blockade has been demonstrated to beneficially affect host immune functions and infection outcome against several intracellular pathogens." (PMID 37637102, 2023). "•Increased infection and gene delivery with continuous perfusion compared to bolus injection.•Significant IL10 and TGF-beta 1 expression in infected hearts, that increased with higher titers." (PMID 37908499, 2023).
infection (continued). "IL-10 has a fundamental role in central and peripheral nervous system homeostasis, reducing neuronal injury during infection, inflammation, ischemia and trauma, and increasing neuron survival and axon regeneration as well as modulating adult neurogenesis." (PMID 37359549, 2023). "CD14+ neutrophils, which mainly increased in number during the recovery stage of infection, were revealed to have a stronger ability to produce cytokines, especially IL-10 and IL-21, than their CD14− counterparts." (PMID 37705063, 2023). "Other infection models showed substantial tissue damage because Th1-polarized CD4+ T cells were unable to transform into an IL-10-producing state." (PMID 36679947, 2023). "An increase of IL-10 serum levels was positively correlated with the survival of pigs to infection with the moderately virulent isolate Netherland’86." (PMID 36680273, 2023). "We hope our findings will provide new insights into the function of fish IL-10 in host immune infections." (PMID 37513733, 2023). "IL-10 is known as human cytokine synthesis inhibitory factor, with multiple and pleiotropic effects in immunoregulation, infection, inflammation, autoimmunity, transplantation, and tumorigenesis." (PMID 36835413, 2023). "In general, we have developed and validated a prognostic model to predict the severity of Omicron variant infection based on six predictors: older age, higher numbers of neutrophils, lower numbers of lymphocytes, and higher levels of PCT, IL-2, and IL-10." (PMID 36936976, 2023). "A gradual increase in IL-10 in gp91-/- lung homogenates following A. fumigatus infection was observed reaching significance at d17 post-infection compared to WT mice (p<0.05)." (PMID 37724291, 2023). "Our study revealed that their colonic contents decreased in the mice after CR infection, especially IL-10 elevation." (PMID 37111225, 2023). "Time significantly affected the level of IL-10, showing an increased level at pre-infection in comparison to parturition (p = 0.0027)." (PMID 37508158, 2023). "The immunomodulating actions of IL-10 were long-time lasting and manifested during the resolution phase of the infection, resulting in decreased demyelination and improved survival." (PMID 37359549, 2023). "The current study also reported that IL-10, IL-13, and IL-33 were significantly increased in severe infection compared to mild infection in children with HBoV." (PMID 37239461, 2023). "Supplementation restored a WT phenotype to DPdh infection, with WT levels of both persistence and inhibition of IL-10 expression." (PMID 38196634, 2023). "At 48 h after infection, IL-10 expression was increased significantly, whereas transcription of IL-6 and IL-12 was decreased significantly, and the presentation of activated caspase-3 protein fell." (PMID 37841250, 2023). "The secretion levels of both TGF-β and IL-10 are subject to the influence of factors such as the severity of infection, parasite developmental stage, and host genetic factors." (PMID 38140198, 2023). "C. burnetii-infected bovine macrophages were also characterized by an upregulation of TNFα and IL-10 at early time-points post-infection." (PMID 36793725, 2023). "Whereas, IL-10, IL-13, and IL-33 were significantly (p < 0.05) increased in severe infection compared to a mild infection in children with HBoV." (PMID 37239461, 2023). "Next, we analyzed the cellular expression of the anti-inflammatory cytokine IL-10 over the course of infection." (PMID 37637102, 2023). "As IL-10 emerged as a crucial mediator of KP induced metabolic changes, but is also known to regulate TFR1 expression in inflammatory macrophages, we applied a specific IL-10 blocking antibody during infection experiments." (PMID 37637102, 2023). "As can be shown, following CsA infection in mouse lung tissue, IL-1β and IL-6 mRNA gene expression was dramatically increased, while IL-10 mRNA gene expression was markedly decreased." (PMID 38259457, 2023).
infection (continued). "Direct infection of nBregs resulting in the secretion of immunoregulatory IL-10 demonstrates that interactions of viral proteins can shift the immune response, generating an environment that favors viral shedding." (PMID 37896776, 2023). "Particularly, IL-6 and IL-10 in the GN-BSI group were significantly higher than those in the GP-BSI group within the first 24 h post-infection." (PMID 37986183, 2023). "IL-10 is a master regulator of immunity during infection with viruses, bacteria, fungi, protozoa and other pathogens, playing a key, and often essential, role in limiting or terminating inflammation and in the consequent host protection." (PMID 37359549, 2023). "In the present study, canine precision-cut lung slices were infected with CDV, demonstrating that infection influences local pulmonary defense responses by ciliary dysfunction and expression of the inhibitory cytokines IL-10 and TGF-β." (PMID 37112814, 2023). "The Tc/EOW group produced a response with a predominance of IFN-γ and IL-12B, and significantly high IL-1β (p = 0.0152) and IL-10 (p = 0.0247), showing the highest concentration at the time of infection of this last cytokine." (PMID 37242721, 2023). "Treatment of Mrp8CreIL-10 fl/fl mice with IL-10 microparticles increased S. aureus burden compared to empty microparticles, confirming the critical role of IL-10 in promoting S. aureus survival during craniotomy infection." (PMID 37179295, 2023). "TGF β1 was the best biomarker of severity during the early phase of infection (AUC: 0.99), followed by IL-10 (AUC: 0.99), IL-6 (AUC: 0.82), and IL-17 (AUC: 0.71)." (PMID 37569646, 2023). "This coincided with reduced serum levels of pro-inflammatory (IL-1β, TNFα, and KC/GRO) and anti-inflammatory markers (IL-10), increased bacterial killing ability of macrophages, and reduced macrophage infiltration into to site of infection." (PMID 36831019, 2023). "Two anti-inflammatory cytokines, IL-10 and GM-CSF trended toward higher values in Gsap knockout rats at baseline and were significantly reduced following infection." (PMID 37366533, 2023). "TNF-α, IL-10, IL-13, and IL-33 were significantly (p < 0.05) increased in severe infection comparison to a mild infection in children with HRSV coinfection with HBoV." (PMID 37239461, 2023). "PRRSV infection was reported to suppress host immune response by regulating IL-10 expression, resulting in increased mRNA levels of IL-1β, IFNα, IL-10, IL-12, TNFα and IFNγ during the first week of infection." (PMID 37547693, 2023). "Kinetic analyses showed that IL-10 production was augmented within 12 h after LDPm infection and reached a maximum at 24–36 h." (PMID 37202419, 2023). "Mechanistically, we found that CVB3 induced an early and potent IL-10 production in the cecal patch at 2 days post infection." (PMID 37896753, 2023). "We observed relatively high down-regulation of the expression of IL-10 compared to the control group during the genogroup I infection on day 6 in koi carp." (PMID 37465154, 2023). "Electrophoretic mobility shift assay (EMSA) demonstrated that BMDC infection with LDPm or LDAm induced the binding of nuclear protein (or proteins) to mouse IL-10 promoter-specific Pr probe, which contained the S site." (PMID 37202419, 2023). "The infection of nBregs resulted in the secretion of IL-10, an immunoregulatory cytokine, which reduced the production of Th1-type cytokines." (PMID 37896776, 2023). "As a source of both itaconate and IL-10, the MDSCs have the potential to shape a local immunometabolic milieu that is conducive to infection." (PMID 37492184, 2023). "Bacterial burden was significantly reduced in the brain and galea of IL-10 KO mice at day 14 post-infection compared to WT animals (respectively)." (PMID 37179295, 2023). "Twenty-four h after infection IL-10, LIF, M-CSF, IL-6, and IL-27 upregulation with the same mAbs was associated with protection in mice." (PMID 37289480, 2023).
infection (continued). "The results also demonstrated that M220+CQ affected the profile of Th cells during infection by increasing IL-10- and IL-17A-positive cells and Treg lymphocytes." (PMID 38256880, 2023). "In contrast to amniotic fluid, IFN‐β, IL‐10, IL‐6, and IL‐27 levels were undetectable in response to infection, and TNF‐α levels were decreased albeit barely above the limit of detection." (PMID 37259639, 2023). "To quantify the effects of both specific inhibitors (STAT-6-inhibition and anti IL-10) on intracellular pathogen survival, we quantified intracellular bacteria after 24 h of infection." (PMID 37637102, 2023). "We also tested the protein level of IL-10 in sera, which can enhance T. gondii invasion into cells at the initial stage of the infection." (PMID 37428723, 2023). "Two manifestations of this macrophage polarization profile were the reduced expression of inducible nitric oxide synthase (Nos2) and the increased expression of interleukin-10 (Il10) during this infection with an obligate intracellular bacterium." (PMID 37624016, 2023). "On the contrary, the koi infected with genogroup IIa elevated the IL-10 expression on days 6 and 11 post-infection." (PMID 37465154, 2023). "Whereas, IL-10, IL-13, and IL-33 were significantly increased in severe infection compared to mild infection in children with HBoV." (PMID 37239461, 2023). "In the fetal amniotic fluid, infection with either Pru or RH induced high levels of IFNγ, IFNβ, IL‐1β, and IL‐10 as compared to saline controls." (PMID 37259639, 2023). "We further observed that LDPm infection stimulated the secretion of another anti-inflammatory cytokine, interleukin-10 (IL-10), from BMDCs." (PMID 37125906, 2023). "Monocyte recruitment to the brain was unaffected at this time point, but was significantly increased at an earlier interval (day 7 post-infection) in IL-10 KO animals that preceded the reduction in bacterial burden." (PMID 37179295, 2023). "Divulging the inner workings of IL-10, specifically how it limits parasite control, and the factors that promote and suppress IL-10 expression during infection is crucial to understanding the immune response to Plasmodium infection." (PMID 37843306, 2023). "Both human and murine model studies confirmed that high IFN-γ and low IL-10 levels were connected to the successful activation of the immune system and the elimination of enteric salmonellosis in the early phase of the infection." (PMID 37106972, 2023). "IL-10 is an anti-inflammatory cytokine vital in determining the outcome of infection with Plasmodium in mice and humans (1, –, 6)." (PMID 37843306, 2023). "Depletion of CD4+ T cells, IL-10, or IL-4 before infection or vaccination ameliorated disease severity but consequently resulted in prolonged viral shedding." (PMID 37896776, 2023). "No immediate explanation was available for this as it is expected that the sex with higher infections would have higher pro-inflammatory cytokines such as IL-6 and lower anti-inflammatory cytokines such as IL-10." (PMID 37018184, 2023). "Serum IL-10 was increased in WT mice 8 hours after infection, whereas VE-Cad ADAM10–/– mice had a minimal increase in IL-10 levels, mirroring the response seen in humans who survive infection." (PMID 37788087, 2023). "Overall, the data suggest that Bhlhe40 negatively regulates IL-10 production in the spleen after infection with P. yoelii and that splenic antigen-specific CD4+ T cells contribute to the elevated IL-10 production in the absence of Bhlhe40." (PMID 37843306, 2023). "Collectively, this work has demonstrated an important role for IL-10 in promoting S. aureus persistence during craniotomy infection." (PMID 37179295, 2023). "The levels of Th1-type cytokines (IFN-γ, TNF-α) and immune inhibitory cytokines (IL-10) in Tigit-/- mice were higher than those in WT mice at 4 and 6 weeks after infection." (PMID 36930687, 2023).